XIST (X inactive specific transcript)
Diseases named in the same sentence as XIST in open-access papers (continued):
Sharing a sentence is not in itself a finding about the gene and the disease.
tumor (continued). "Of the 124 DMX genes, 11.86% were significantly more expressed in female compared to male-derived tumours (Student’s t-test, p<0.05), suggesting a potential sex-specific mechanism of XIST-mediated gene regulation in lung tumours." (PMID 31419261, 2019). "The high-XIST male-derived tumours exhibited female-level XIST expression (Student’s t-test, p = n.s.), and both male and female high-XIST systems had greater expression of XIST than low-XIST males (Student’s t-test, p<0.0001)." (PMID 31419261, 2019). "In the Lv-XIST shRNA transfected tumor, XIST expression was significantly decreased compared to the Lv-scramble transfected tumors and untreated tumors." (PMID 31189404, 2019). "Our current meta-analysis evaluated the association between XIST expression levels and tumor types, LNM, DM, tumor stages, DFS and OS." (PMID 29568404, 2018). "XIST, as the shared gene, has been confirmed to participate in tumor-suppressive biological processes; its high expression corresponds with a specific pathological pattern." (PMID 30322114, 2018). "Two different results indicate that the abnormal expression level of XIST can be affected by different experimental conditions or tumor tissues." (PMID 29568404, 2018). "Data from other 2 studies reported XIST functions as the tumor suppressors were collected and reanalyzed." (PMID 29568404, 2018). "XIST exerts its oncogenic function by decreasing blood-tumour barrier permeability and promoting angiogenesis through the XIST-miR-137-Rac1 pathway or the XIST-miR-137-FOXC1/ZO-2 pathway." (PMID 29552296, 2018). "KYSE150 cells with stable expression of short hairpin RNAs targeting XIST (sh#1 or sh#2) or scramble sequence (NC) were inoculated into the dorsal flank of nude mice and the tumor volume was monitored." (PMID 29100288, 2017). "In vivo studies also showed that knockdown of XIST repressed tumor growth and induced high survival rates in nude mice." (PMID 28187439, 2017). "Collectively, XIST is upregulated in ESCC tumor tissues and acts as an independent prognosis predictor for ESCC." (PMID 29100288, 2017). "In the case of glioma, lncRNA XIST exerts tumor-suppressive functions by up-regulating miR-152 in glioblastama stem cells." (PMID 28881797, 2017). "LncRNA XIST expression was negatively associated with miR-497 expression, while positively associated with MACC1 expression in the tumor tissues." (PMID 27911852, 2017). "Consistent with other results, our study affirmed that depletion of SAF-A fully mislocalizes Xist RNA in mouse Neuro 2A tumour cells and impacts XIST expression/localization in pluripotent stem cells." (PMID 28947659, 2017). "Knockdown of XIST exerted a tumor-suppressive function by decreasing GSC proliferation, migration and invasion as well as by promoting apoptosis." (PMID 28187439, 2017). "After XIST knockdown, mice tumor size and weight was reduced, compared with LV-sh-contr infected mouse tumor." (PMID 29371940, 2017). "The result showed that in both male and female patients, the expression of lncRNA XIST was significantly higher in tumor tissues than that of adjacent normal tissues (*P<0.05)." (PMID 28837144, 2017). "Lentivirus mediated knockdown of XIST inhibited proliferation, migration and invasion of esophageal squamous cancer cells in vitro and suppressed tumor growth in vivo." (PMID 29100288, 2017). "Univariate analysis indicated that tumor size (P = 0.019), differentiation state (P = 0.048), TNM stage (P = 0.000) and XIST expression level (P = 0.005) were significantly associated with overall survival of ESCC patients." (PMID 29100288, 2017). "In accordance with our results, it has been found that lncRNA XIST plays an important role in different tumor types." (PMID 28837144, 2017).
tumor (continued). "Clinicopathological analysis has shown that over-expression of XIST correlates with tumor progression." (PMID 29371940, 2017). "XIST levels were significantly decreased in HCC and associated with histological grade and tumor-node-metastasis stage." (PMID 28388883, 2017). "Furthermove, an inverse relationship was found between lncRNA XIST and miR-101, and knockdown of lncRNA XIST exerted its tumor-suppressive effects at least in part through regulating miR-101 to modulate EZH2 expression." (PMID 27620004, 2016). "For example, XIST expression is upregulated in glioblastoma tissue and stem cells and its knockdown exerts tumor suppressive functions." (PMID 26992233, 2016). "Functionally, knockdown of lncRNA XIST exerted tumor-suppressive effects by inhibiting cell proliferation, migration and invasion in vitro and tumor growth and metastasis in vivo." (PMID 27620004, 2016). "Conversely, the deletion of XIST from the blood compartment in mice triggers a myelodysplastic and highly proliferative neoplasm with a very high penetrance (100%)." (PMID 26992233, 2016). "The number, organization, and intensity of XIST RNA domains varied substantially between tumors and even among cells of the same tumor." (PMID 25653311, 2015). "We analyzed seven tumors using a tumor stamp technique with fresh samples to evaluate the degree of enrichment of H3K27me3 at sites of XIST RNA accumulation." (PMID 25653311, 2015). "Thus, XIST has been regarded as an oncogene interacting with a number of tumor-suppressing miRNAs, such as miR-152, miR-101, miR-124, miR-29c, miR-29a, miR-140, miR-367/141, and miR-133a." (PMID 41601966, 2026). "Several lncRNAs, such as XIST, PVT1, and LINC01638, are significantly upregulated in pancreatic cancer (PC) tissues compared to adjacent normal tissues, and are associated with enhanced tumor proliferation, migration, and invasion." (PMID 41437175, 2025). "Moreover, abnormal XIST expression has been observed in various cancers, and studies have shown that transcription of XIST affects tumor progression." (PMID 40981384, 2025). "al (2021) reported the role of XIST in regulating immune cells, including macrophages, in the tumor microenvironment by the Xist/miR-101-3p/KLF6/C/EBPα, which might extend to NK cells through similar epigenetic and gene regulatory mechanisms." (PMID 40781182, 2025). "XIST contributes to tumor progression by regulating two TGFβ-related pathways." (PMID 41437175, 2025). "XIST is more highly expressed in patients with high tumor and peritumoral CD4 inflammation." (PMID 40352941, 2025). "Of note, MN1 exerts a pro-tumor effect through the XIST/miR-15a-5p/MN1/FZD2 signaling axis, and its significantly high expression is observed in female patients with poor prognosis, which may be an important molecular basis for the gender difference in BLCA." (PMID 41019085, 2025). "Knockdown of XIST exerts tumor-suppressive functions in human glioblastoma stem cells." (PMID 39639337, 2024). "After that, we re-subtypeed tumor cells, and annotated them according to each cell marker gene, and identified six tumor cell subtypes: C0 XIST+ tumor cells, C1 SCGB2A1+ tumor cells, C2 IGF2+ tumor cells, C3 UBE2C+ tumor cells, C4 TFF3+ tumor cells and C5 IGFBP3+ tumor cells." (PMID 39896800, 2024). "Our study compared the expression of XIST in 430 tumor samples and 195 normal ovarian tissues." (PMID 39546568, 2024). "To investigate further, we examined XIST expression across different tumor histological grades." (PMID 39546568, 2024). "Future studies will be necessary to define the functional significance and underlying mechanisms of other tumor supportive cytokines/chemokines (i.e., IL1A/B, LIF, G/M-CSF and CXCL2/3) and inflammatory proteins (i.e., S100P and S100A9) in mediating XIST regulation of tumor growth and CSC activity." (PMID 36922677, 2023).
tumor (continued). "In addition to its well-established role in X chromosome inactivation (XCI) during early embryogenesis, accumulating evidence suggests that aberrant XIST expression in post-XCI somatic cells plays a role in tumor development and progression." (PMID 36922677, 2023). "Collectively, XIST levels in serum may be used as a tumor marker for TC promoted by HIF-1a, which could be treated using artemisinin." (PMID 37036874, 2023). "This suggests that EMT progression was induced in XIST+ tumor cells." (PMID 37430270, 2023). "XIST is stably expressed in serum and can be used as a tumor marker." (PMID 37036874, 2023). "As let-7 miRNAs including let-7a directly repress IL-6 cytokine production in breast epithelial cells, our data suggest a potential activity of XIST by repressing let-7a-2-3p in ALDH- bulk tumor cells to increase IL-6 cytokine production, which in turn promotes ALDH+ CSCs." (PMID 36922677, 2023). "We suggest that this double positive feedback loop of XIST and STAT3 may contribute to the dysregulation of XIST in BC and other tumor types." (PMID 36922677, 2023). "Similarly, the functional relevance and mechanisms of XIST in inhibiting tumor suppressive cytokine/chemokines (i.e., IL-7, IL-15, and IL-18) need to be determined." (PMID 36922677, 2023). "To explore the potential mechanisms by which XIST regulates tumor growth and CSC activity, we FACS sorted ALDH- and ALDH+ cells from DOX-untreated SUM159-shXIST cells, which were replated and treated with or without DOX for 3 days and subjected to next-generation RNA sequencing (RNAseq)." (PMID 36922677, 2023). "XIST levels in serum may be used as a tumor marker for TC promoted by HIF-1a, which could be treated by artemisinin." (PMID 37036874, 2023). "Then, we clarify the regulatory mechanism of XIST’s tumour suppressive function on female HCC." (PMID 38148658, 2023). "As this marker is known to be positively correlated with OC burden, XIST might also increase with tumour progression." (PMID 38203310, 2023). "In summary, XIST may regulate tumour progression by regulating the expression of miRNA-96-5p, miRNA-153-3p, and miRNA-182-5p; however, its complex regulatory mechanism requires further experimental validation." (PMID 36038831, 2022). "This indicates that XIST exhibited anti-tumor effects in HCC by sequestering miR-221-3p." (PMID 35723009, 2022). "Its overexpression has been shown to reverse XIST’s anti-tumor effects in OSCC." (PMID 35258410, 2022). "In vivo experiments showed that inhibiting the expression of XIST could delay the progression of the tumour after subcutaneous inoculation in nude mice." (PMID 36038831, 2022). "Moreover, Li and colleagues observed that lncRNA XIST induces tumor metastasis and by Zinc finger E-box-binding homeobox 2 (ZEB2) in NSCLC." (PMID 35453680, 2022). "Subsequent studies have shown that XIST is involved in tumor progression." (PMID 36309693, 2022). "XIST acts as a tumor suppressor in these cancers by repressing metastasis and cell growth." (PMID 35723009, 2022). "In addition, the knockdown of lncRNA XIST or overexpression of miR-137 repressed tumor growth and TGF-β1-induced EMT in A549 and H1299 cells." (PMID 35453680, 2022). "Animal studies validated that XIST knockdown induces tumor growth in vivo." (PMID 35723009, 2022). "lncRNA XIST was first found to be able to participate in the initiation stage of X chromosome inactivation, and it can participate in the process of various cancer diseases, and affect the proliferation and invasion of tumor cells." (PMID 35109760, 2022). "After down-regulating the expression of XIST, the cell proliferation, migration and invasion in vitro, tumor growth and lung metastasis in vivo were inhibited, indicating that BMSCs derived exosomal XIST play a role in promoting cancer, which is consistent with most research reports." (PMID 36309693, 2022).
tumor (continued). "However, down-regulation of XIST reduced tumor volume and weight, decreased Ki67 positive staining intensity, and inhibited lung metastasis." (PMID 36309693, 2022). "The xenograft tumor model was used to explore the biological function of XIST in vivo." (PMID 35899235, 2022). "Finally, the knockdown of lncRNA XIST or upregulation of miR-744 suppresses tumor growth and metastasis in NSCLC." (PMID 35453680, 2022). "Compared with previous articles, the novelty of this study lies in the confirmation that XIST downregulation might inhibit tumor migration, invasion, and glycolysis, and the construction of a novel network mechanism of the XIST-miR-320d-ARF6 axis." (PMID 35899235, 2022). "Taken together, serum exo‐XIST which could reflect tumour burden during treatment may be specifically secreted and released by TNBC cells." (PMID 33949761, 2021). "Importantly, our research manifested that XIST expression was markedly elevated in RB tissues and cell lines, and remarkably related to RB staging and tumor invasion." (PMID 33942699, 2021). "Histological analysis further verified the tumor-promoting effect of KCNQ1OT1/XIST overexpression." (PMID 34521445, 2021). "Finally, we utilized the CRISPR/Cas9 system to knock out (KO) the XIST gene, and to evaluate its role in tumor development in vivo." (PMID 34295808, 2021). "We also identified five lncRNAs with abundant expression (LRRC75A-AS1, HYMAI, NEAT1, XIST and FTX) were closely associated with tumor progression, which may suggest to be the biomarker for the malignancy of GIST." (PMID 34557343, 2021). "Our study revealed that XIST KO via the CRISPR/Cas9 system is able to inhibit tumor growth." (PMID 34295808, 2021). "Effect of altered XIST and miR-149-3p on tumor growth in vivo was observed." (PMID 33542185, 2021). "Furthermore, the impacts of altered XIST and miR-149-3p on tumor growth in vivo was observed and we found that deleted XIST and promoted miR-149-3p restrained OC development in vivo." (PMID 33542185, 2021). "Thus, the lncRNA XIST played a critical role in BCBM in a gender-specific manner by influencing both tumor cells and the TME." (PMID 34707990, 2021). "In addition to these types of malignancies, functional studies have verified the impact of XIST in the pathogenesis of almost all kinds of neoplasms." (PMID 34179019, 2021). "Furthermore, KCNQ1OT1/XIST aggravated tumor growth in vivo by regulating endoplasmic reticulum stress and cell apoptosis." (PMID 34521445, 2021). "Several lncRNAs with abundant expression (LRRC75A-AS1, HYMAI, NEAT1, XIST and FTX) were closely associated with tumor size, which may suggest to be biomarkers for the GIST malignancy." (PMID 34557343, 2021). "XIST also exhibits anti-tumor properties in a small subset of tumors, such as lymphomas." (PMID 34930117, 2021). "Furthermore, XIST was shown to regulate tumour cell migration, proliferation, and invasion, in NSCLC." (PMID 33255394, 2020). "Increased XIST level has a positive correlation with the progression of tumor." (PMID 32061057, 2020). "Knockdown of XIST inhibited tumor growth and prolonged the survival time in nude mice." (PMID 32489472, 2020). "This suggests that XIST may play different roles as a tumor suppressor gene or oncogene in different tumor tissues." (PMID 32489472, 2020). "Inhibition of lncRNA XIST reduces the NBL tumor volume in mice." (PMID 32886453, 2020). "Cells stably expressing shXIST or shNC were transfected with anti-miR-204-5p or anti-miR-204-5p-NC to evaluate whether XIST mediates the tumor-suppressive effects of miR-204-5p." (PMID 32489472, 2020). "In addition, PTN another gene effected by XIST is a heparin-binding growth factor that is involved with tumour progression." (PMID 33255394, 2020). "A tumor metastasis model by tail-vein injection of tumor cells was used to investigate whether XIST promotes metastasis." (PMID 33364236, 2020).
tumor (continued). "In addition, in TGCTs, XIST is found to be expressed in tumor cells given the supernumerary X chromosomes, due to the initial step of polyploidization." (PMID 31533343, 2019). "However, SE samples were found to exhibit a higher relative amount of the demethylated XIST fragment as compared with NS (p < 0.001), with the same occurring when compared individually to EC and TE tumor subtypes (adjusted p-value < 0.05)." (PMID 31533343, 2019). "As for the contribution of lncRNAs XIST and TSIX in BC, their precise role is largely unknown with minimal studies reporting lncRNA XIST as a tumor suppressor lncRNA whose level is downregulated in BC, with no suggestions about lncRNA TSIX role in BC." (PMID 31998636, 2019). "Therefore, XIST is also a pro-cancerous factor in PC cells, and silencing its expression can inhibit tumor cellular processes, such as the activities of proliferation and invasion." (PMID 31213574, 2019). "Finally, the potential value of methylation-specific tumor DNA fragments (i.e., XIST promotor) as well as embryonic microRNAs as molecular biomarkers for cancer detection in liquid biopsies will be presented." (PMID 30634670, 2019). "XIST has been demonstrated to play oncogenic function in multiple tumours." (PMID 31066476, 2019). "As a sex-specific lncRNA, XIST presents the opportunity to study human cancer cells from tumours with dichotomous XIST expression and determine how the presence of this transcript in the system could be causing downstream gene expression changes." (PMID 31419261, 2019). "Compared with the control group, xenografts in the anti-XIST group were much smaller and lighter, and co-transfection with miR-200c inhibitor could partially revert the inhibition of tumour growth." (PMID 29559853, 2018). "Moreover, they all found that an inverse relationship between lncRNA XIST and miR-101, and knockdown of lncRNA XIST exerted its tumor-suppressive effects at least in part through regulating miR-101 to modulate EZH2 expression." (PMID 29556138, 2018). "In addition, the in vivo tumourigenesis assay also demonstrated that XIST knockdown resulted in a dramatic decrease in the size of tumour growth." (PMID 29559853, 2018). "Therefore, we conducted a meta-analysis to evaluate the potential value of lncRNA XIST as a novel biomarker for predicting tumor prognosis, which provided a reference for the follow-up study." (PMID 29556138, 2018). "The OS of tumor patients with high expression of lncRNA XIST in digestive system tumors was lower than that in low expression group (HR = 1.67, 95% CI 1.11–2.51, p = 0.014), but not statistically significant in other tumors (HR = 1.39, 95% CI 0.71–2.74, p = 0.339)." (PMID 29556138, 2018). "Moreover, higher XIST expression was correlated with larger tumor size, advanced N stages and TNM stages." (PMID 30463570, 2018). "Furthermore, elevated expression levels of XIST were connected with distant metastasis and tumor stage." (PMID 29752340, 2018). "Moreover, patients with higher XIST expression in the tumor tissues were prone to developing LNM, DM, as well as increased probability of high tumor stages." (PMID 29568404, 2018). "We monitored the tumor volume and weight in response to XIST knockdown." (PMID 30463570, 2018). "With regard to clinicopathological characteristics, our results indicated that elevated expression levels of XIST represented a greater possibility of distant metastasis (pooled OR = 2.28, 95% CI: 1.29–4.02) and high tumor stage (pooled OR = 2.25, 95% CI: 1.67–3.03)." (PMID 29752340, 2018). "Combined these studies with our data, we speculated that XIST may play distinct roles depending on the tumor type and may interfere with different miRNAs in different tumors." (PMID 29100288, 2017). "Altogether, knockdown of XIST suppresses tumor growth via regulation of miR-101/EZH2 axis in vivo." (PMID 29100288, 2017). "The knockdown of XIST by short-hairpin RNA exerts a tumor suppressive function in GSCs." (PMID 28293170, 2017).